NBPF12 (NBPF member 12)
Synonyms: COAS1; KIAA1245
Tractability: PROTAC: ubiquitination databases record sites on it.
Gene: Protein-coding gene on chromosome 1 (146,938,324 to 146,996,202, forward strand). Ensembl gene ENSG00000268043.
Subcellular location: Cytoplasm
Subcellular location (Human Protein Atlas): Cytosol; Primary cilium; Cytokinetic bridge; End piece; Golgi apparatus; Microtubules; Mid piece; Principal piece; Vesicles
Gene Ontology:
Cellular component: cytoplasm
Genetic constraint (gnomAD): Loss-of-function variants: 82 observed, 57.07 expected, observed/expected ratio (o/e) 1.44, 90% interval 1.2 to 1.73. The synonymous counts are far from expectation, so gnomAD's model fits this gene poorly and the ratio says little. Missense variants: 793 observed, 558.54 expected, observed/expected ratio (o/e) 1.42, 90% interval 1.34 to 1.51. Synonymous variants: 249 observed, 203.32 expected, observed/expected ratio (o/e) 1.22, 90% interval 1.1 to 1.36.
Homologues: Paralogues in human: NBPF14 (78% identical), NBPF10 (78% identical), NBPF26 (78% identical), NBPF1 (74% identical), NBPF9 (62% identical), NBPF8 (62% identical), NBPF20 (60% identical), NBPF19 (60% identical), NBPF11 (55% identical), NBPF15 (44% identical), NBPF3 (32% identical), NBPF4 (21% identical), and 1 more.
Diseases named in the same sentence as NBPF12 in open-access papers:
NBPF12 is named in the same sentence as 9 diseases in open-access papers, as found by Europe PMC text mining. Sharing a sentence is not in itself a finding about the gene and the disease. The quoted sentences say what the papers report.
breast carcinoma (2 papers, 2017 to 2025). "These genes, including NBPF12, CCDC9B, and GABRE (which encodes a subunit of the GABA receptor), are known to play roles in breast cancer progression." (PMID 41285961, 2025).
neuroblastoma (2 papers, 2015 to 2026). Neuroblastoma (NB) is the most common solid, extracranial childhood tumor. "NBPF12 encodes a member of the neuroblastoma breakpoint family, which plays a crucial role in neuroblastoma development and human evolution and is regulated by NF-κB20." (PMID 41583513, 2026). "Three fast evolving genes (NBPF11, NBPF12 and NBPF15) that are differentially expressed in both sPTB and PE are part of a neuroblastoma breakpoint (NBPF) gene family that has been shown to exhibit neuron-specific expression and copy number variations." (PMID 26641094, 2015).
autism (1 paper, 2024). Persistent deficits in social interaction and communication and interaction as well as a markedly restricted repertoire of activity and interest as well as repetitive patterns of behavior. "NBPF12 is part of the neuroblastoma breakpoint family, which has been associated with an array of traits, such as autism, psoriasis and various cancers." (PMID 38491524, 2024).
non-small cell lung carcinoma (1 paper, 2017). A group of at least three distinct histological types of lung cancer, including non-small cell squamous cell carcinoma, adenocarcinoma, and large cell carcinoma. "In contrast, overexpression of NBPF12 has been found in several cancers including sarcomas, and non-small-cell lung cancer." (PMID 29029473, 2017).
ovarian carcinoma (1 paper, 2025). A malignant neoplasm originating from the surface ovarian epithelium. "Using independent ovarian cancer cohort (TCGA-OV) we also confirmed high frequencies of mutational alterations in the NBPF gene family including NBPF1, NBPF9, NBPF10, NBPF12 and NBPF14 (> 50%)." (PMID 41316472, 2025).
cancer (4 papers, 2017 to 2026). A tumor composed of atypical neoplastic, often pleomorphic cells that invade other tissues. "NBPF12 exhibited significant downregulation in cancer tissues compared to adjacent normal tissues, while the other five model genes exhibited significant upregulation." (PMID 41583513, 2026).
NBPF12 also shares sentences with these, for which no sentence is quoted: psoriasis (1 paper); sarcoma (1); tumor (1).